FAM215A (family with sequence similarity 215 member A)
Synonyms: APR-2; C17orf88; LINC00530
Gene: Long non-coding RNA gene on chromosome 17 (43,917,194 to 43,921,042, forward strand). Ensembl gene ENSG00000267496.
Diseases named in the same sentence as FAM215A in open-access papers:
FAM215A is named in the same sentence as 33 diseases in open-access papers, as found by Europe PMC text mining. Sharing a sentence is not in itself a finding about the gene and the disease. The quoted sentences say what the papers report.
melanoma (3 papers, 2020 to 2024). A malignant, usually aggressive tumor composed of atypical, neoplastic melanocytes. "Inhabited FAM215A expression results in the increasing death of melanoma cells." (PMID 33274190, 2020).
prostate carcinoma (3 papers, 2017 to 2021). A carcinoma that arises from epithelial cells of the prostate gland. "The OS-related prognostic model was constructed based on the five ARGs (FAM215A, FDD, MYC, RHEB, and ATG16L1) and significantly stratified prostate cancer patients into high- and low-risk groups in terms of OS (HR = 6.391, 95% CI = 1.581– 25.840, P < 0.001)." (PMID 32264916, 2020). "However, the function of FAM215A and FDD gene has not been reported in prostate cancer, indicating that functional studies on these genes may help us to understand the prognosis-related biological behavior of bladder cancers more accurately." (PMID 32264916, 2020).
ovarian carcinoma (2 papers, 2020). A malignant neoplasm originating from the surface ovarian epithelium. "As for the other genes related to CKD, the function of lnRNA-FAM215A has been fewer investigated, and a meta-analysis report showed that the high expression of FAM215A was associated with longer overall survival in ovarian cancer." (PMID 33274190, 2020). "Conversely, in ovarian cancer, FAM215A is associated with favorable overall survival." (PMID 32295144, 2020).
hepatocellular carcinoma (1 paper, 2020). A malignant tumor that arises from hepatocytes. "In the current study, we show that FAM215A is highly expressed in human hepatoma samples and associated with clinical markers of tumor progression, including tumor size, vascular invasion, and pathologic stage." (PMID 32295144, 2020). "FAM215A is a novel dysregulated lncRNA that our previous microarray analysis identified as being highly expressed in human hepatoma tissues." (PMID 32295144, 2020). "Our previous microarray analysis identified the lncRNA, FAM215A, as being highly expressed and dysregulated in human hepatoma samples." (PMID 32295144, 2020).
metastatic tumors (1 paper, 2020). "In metastatic tumors found in the lungs of such mice, LAMP2 expression was decreased in mice with FAM215A-knockdown cell-derived tumors compared to mice injected with control cells." (PMID 32295144, 2020).
tumor (16 papers, 2007 to 2025). "Indeed, our data showed that FAM215A knockdown was associated with decreased tumor growth and further repression of the tumor size in DOX-treated mice." (PMID 32295144, 2020). "Our results therefore collectively suggest that FAM215A induces tumor progression, metastasis, and doxorubicin resistance, potentially through LAMP2." (PMID 32295144, 2020). "Together, our findings clearly indicate that FAM215A increases tumor progression and DOX resistance in HCC by interacting with and increasing the stability of LAMP2." (PMID 32295144, 2020). "Our results collectively indicate that FAM215A induces tumor metastasis, enhances tumor growth, and increases the doxorubicin resistance capacity in HCC." (PMID 32295144, 2020). "The expression levels of FAM215A and LAMP2 were decreased in the tumor tissues with FAM215A-knockdown cell-derived tumors compared to mice injected with control cells." (PMID 32295144, 2020). "In conclusion, we herein show for the first time that the lncRNA, FAM215A, is highly expressed in HCC, where it interacts with and prevents the ubiquitination of LAMP2 to increase tumor progression and decrease doxorubicin sensitivity." (PMID 32295144, 2020). "We show for the first time that FAM215A is overexpressed in HCC, and its expression level correlates with tumor size, vascular invasion, and pathology stage." (PMID 32295144, 2020). "Together, our results show that the lncRNA, FAM215A, is highly expressed in HCC, where it interacts with and stabilizes LAMP2 to increase tumor progression while decreasing doxorubicin sensitivity." (PMID 32295144, 2020). "Indeed, high FAM215A expression was significantly correlated with tumor size, vascular invasion, and pathology stage in HCC, and FAM215A upregulation was also closely correlated with the recurrence-free survival of HCC patients." (PMID 32295144, 2020). "Results showed that AC104971.3 (p < 0.01), AC021678.2 (p < 0.01), LINC02413 (p < 0.05), AL161781.2 (p < 0.05), and LY86-AS1 (p < 0.01) were significantly downregulated in clinical LUAD tumor tissues, and that FAM215A expression was not significantly different but slightly increased in tumor samples." (PMID 36428951, 2022).
cancer (5 papers, 2015 to 2023). A tumor composed of atypical neoplastic, often pleomorphic cells that invade other tissues. "In addition to its regulation of doxorubicin sensitivity, FAM215A also affects the sensitivity of cancer cells to other anticancer drugs, such as cisplatin and sorafenib." (PMID 32295144, 2020). "Based on the FAM215A influence on different drugs’ sensitivity, we examined the lysosome expression of strong correlation with the multidrug resistance (MDR) of cancer cells." (PMID 32295144, 2020).
FAM215A also shares sentences with these, for which no sentence is quoted: breast carcinoma (3 papers); Cerebral ischemia (2); infection (2); kidney disease (2); lung carcinoma (2); neuroblastoma (2); apical periodontitis (1); bladder cancers (1); cholangiocarcinoma (1); colitis (1); desminopathies (1); Diabetes (1); endometritis (1); gastric cancer (1); hyperlipidemia (1); iron metabolism disorder (1); liver cancer (1); liver fibrosis (1); malaria (1); multiple myeloma (1); Myocardial fibrosis (1); osteosarcoma (1); Parkinson (1); rheumatoid arthritis (1); Stroke (1); tongue cancer (1).